TRPV1 (transient receptor potential cation channel subfamily V member 1)
Diseases named in the same sentence as TRPV1 in open-access papers (continued):
Sharing a sentence is not in itself a finding about the gene and the disease.
cancer (continued). "The decreased expression of TRPV1 and TRPV4 in cancer-bearing animals, as compared to sham, does not necessitate their decreased activity." (PMID 29637027, 2018). "Here, we also confirm the relationship between TRPV1 and the gram-negative bacterial receptor TLR4 by their concurrent expression on DRG cells of the cancer-induced rat model." (PMID 29637027, 2018). "The analgesic effects of spinal TRPV1 antagonism in mice CCI model were successfully repeated without malignant hyperthermia, but the authors proposed a novel mechanism engaging LTD of TRPV1-positive inhibitory neurons." (PMID 26885404, 2016). "The diminished expression of TRPV1 and TRPV4 in cancer-bearing animals does not represent a poorly executed function but rather an interconnection between the receptor’s continuous activation by the distant invasive tumor and the increased nociception afterward." (PMID 38730655, 2024). "Our data suggests that blocking long-term TRPV1 sensitization may have a role in preventing development of bortezomib induced CIPN, at least in nociceptors, which should not impact the cancer chemotherapeutic activity of the agent." (PMID 38052846, 2023). "While we investigated the nociceptive neuron plasticity through the expression of TRPV1 and CGRP expression, we did not evaluate mediators released specifically from cancer cells that could affect nociceptive signaling." (PMID 36172037, 2022). "Further, TRPV1 initiates direct negative feedback on the EGFR, and blocking EGFR may keep cancer cells from developing and growing." (PMID 33379302, 2020). "In cancer murine 4T1 and human MCF-7 mammary carcinoma cells, the action of JWH-015 seems to be complex, since it is not mediated either by CB1R or CB2R, or by GPR55, TRPV1, or TRPA1 receptors." (PMID 31214034, 2019). "Notably, TRPV1 expression had a negative correlation with the expression of MKI67, a marker for cell proliferation, in pan-cancer (p = 3.04 × 10−93; r = −0.28) and in five cancer types (p < 0.05)." (PMID 36304985, 2022). "In this light, the activation of TRPV1 in the presence of PI3K/Akt and Ras/Raf/MEK/ERK pathway inhibitors—potentially including P2Y2 and EGFR antagonists—may promote cancer cell apoptosis through [Ca2+]i signaling without the induction of proliferative mechanisms." (PMID 32545311, 2020).
tumor (155 papers, 2010 to 2026). "On the other hand, activation of TRPV1 has been linked to pro-apoptotic signaling, indicating that its modulation must be carefully tailored to the tumor context." (PMID 40869148, 2025). "Gradual loss of low TRPV1 expression suggests tumor progression, increased staging, higher malignancy, and worse prognosis." (PMID 40007993, 2025). "TRPV1 upregulation is associated with decreased tumor proliferation, making it a therapeutic target that correlates with enhanced antitumor immune responses." (PMID 39407657, 2024). "The loss of TRPV1 staining correlated with the Fuhrman grade of the tumor and predicted poor survival." (PMID 37240443, 2023). "In fact, chemical ablation of TRPV1-positive afferents by capsaicin or resiniferatoxin has a profound effect on tumor growth and metastasis; for example, it caused early metastatic spread in a murine model of triple negative breast cancer." (PMID 37240443, 2023). "Here, we showed that the cisplatin resistance of tumor cells is closely linked to secretory autophagy-mediated EGFR hyperactivation via the transcriptional induction of TRPV1 by NANOG." (PMID 37165076, 2023). "To investigate TRPV1 as a target for impeding NANOG-driven autophagy in cisplatin-resistant tumor cells, we monitored TRPV1 expression in cisplatin-susceptible or -resistant tumor cells." (PMID 37165076, 2023). "It indicates that TRPV1 expression is positively associated with tumor prognosis through multiple mechanisms." (PMID 36304985, 2022). "To analyze the correlation between TRPV1 and various types of tumor‐infiltrating immune cells, we concentrated on the association between the expression level of TRPV1 mRNA and immune marker sets of each type of immunocytes." (PMID 35620019, 2022). "It supports a previous study showing that the tumor suppression role of TRPV1 is associated with its positive correlation with antitumor immune infiltration in ccRCC." (PMID 36304985, 2022). "Evidence supports that tumor cells cause an acidic environment and TRPV1 senses the enhancement of protons in tissues, leading to neuronal activation and pain." (PMID 36138983, 2022). "Then, the associations of TRPV1 with survival and immune cell infiltration were respectively analyzed by application of Kaplan-Meier (KM) plotter and Tumor IMmune Estimation Resource (TIMER), two website servers for bioinformatic analysis." (PMID 32913462, 2020). "We further elucidated the underlying mechanisms of how TRPV1 inhibits GC cell proliferation in vitro and tumor growth in vivo." (PMID 33008449, 2020). "To study the molecular mechanisms underlying the process of tumor infiltration of the peripheral nerves, we quantified two key transducers, TRPV1 and TRPV4, within the neuronal cells by immunofluorescence and Western blotting." (PMID 29637027, 2018). "TRPV-1 also negatively regulates the epidermal growth factor receptor in intestinal epithelial cells and reduces the risk of neoplasia development." (PMID 26888607, 2016). "On the other hand, loss of TRPV1 during the progression of tumor with the acquisition of a more invasive phenotype stimulates studies on the mechanisms responsible to the expression of TRPV1 in TCC of human bladder." (PMID 22523714, 2012). "Through a comprehensive strategy combining proteomic profiling, Transgenic Adenocarcinoma of the Mouse Prostate (TRAMP) mouse modeling, and validation in human prostate biopsies, we assessed TRPV1 expression, its functional role, and its association with tumor markers." (PMID 41694593, 2026). "Interestingly, TRPV1 was significantly overexpressed in cisplatin-resistant tumor cells compared to cisplatin-susceptible tumor cells." (PMID 37165076, 2023). "A reduction in pain-related gene expression in response to trigeminal nerve injury has been previously reported, suggesting that tumor-induced nerve injury may be the driving force for this loss of Trpv1 expression in tumor-bearing male mice." (PMID 36172037, 2022).
tumor (continued). "In this study, we hypothesized that TRPV1 is a tumor suppressor in CRC development as well as the underlying mechanism." (PMID 31183372, 2019). "The integration of these strategies with TRPV-1 activation strategies and developments of more efficient differentiation strategies will enable us to fabricate bioengineered tissues with low risk of tumour formation for regenerative medicine." (PMID 26888607, 2016). "Interestingly, the hyperthermia alone caused an obvious apoptotic behavior at the tumor section as verified by the enhanced red fluorescence, whereas SB705498 or TRPV1 knockdown further amplified the apoptotic levels at the tumor sections caused by the hyperthermia." (PMID 37120615, 2023). "Thus, TRPV-1 activation might be helpful to reduce the risk of tumour formation following iPS cell-derived cell transplantation." (PMID 26888607, 2016). "For instance, in HPV-positive head and neck cancers, small extracellular vesicles secreted by tumor cells are taken up by TRPV1+ nociceptors, triggering neuronal hyperexcitability and pain behaviors, identifying a novel mechanism of cancer-induced nociception." (PMID 41601691, 2026). "We next explored the downstream consequences of decreased neuronal excitability by examining key neuropathic sensitization markers, including CGRP, transient receptor potential vanilloid 1 (TRPV1), and substance P (SP), in tumor-bearing bones." (PMID 41576171, 2026). "TRPV1 is involved in tumor angiogenesis by regulating the expression and function of VEGF and its receptors." (PMID 40007993, 2025). "Decreased expression of TRPV1 protein in GC tissues was positively correlated with tumor size, histological grade, lymphatic metastasis, and clinical stage." (PMID 40007993, 2025). "The major bioactive alkaloid in Piper nigrum, acts as a TRPV1 agonist, influencing apoptosis and oxidative stress in tumor cells." (PMID 40565152, 2025). "This elevated temperature activated the TRPV1 channel, leading to a substantial influx of Ca2+ into the tumor cells." (PMID 40813985, 2025). "The repeated activation of TRPV1-positive sensory neurons reduces intra-tumour CD4+ T cells and possibly promotes tumour growth." (PMID 39940997, 2025). "The release of capsaicin-activated TRPV1 in the TME enhanced the expression of PD-L1 on the surface of tumor cells and promoted the recruitment of T cells into the TME, increasing immunoreactivity." (PMID 38734935, 2024). "Similar to the developmental ablation of TRPV1 neurons, their chemoablation post-development resulted in a similar decrease in tumor growth compared to controls." (PMID 39302290, 2024). "Macrophages in the tumor microenvironment can also activate sensory nerve endings via the interleukin-23 (IL23)/IL17A/TRPV1 axis." (PMID 38339399, 2024). "Tumor cells can also generate formaldehyde, which, in concert with the acidic microenvironment, can synergistically activate TRPV1." (PMID 38339399, 2024). "Regarding carcinogenesis, the involvement of TRPV1 as a tumor suppressor has been described in various carcinogenic pathways, including breast cancer, urothelial cell carcinoma and thyroid cancer." (PMID 39125864, 2024). "Nevertheless, our tracing in tumor-bearing nociceptor-neuron-ablated and intact animals was sufficient to functionally implicate TRPV1-expressing neurons in this communication." (PMID 39302290, 2024). "The developmental ablation of TRPV1 neurons can lead to unintended effects on tumor innervation and behavior." (PMID 39302290, 2024). "TRPV1 activation promotes the proliferation of tumor infiltrating lymphocytes (TILs) and the secretion of immune factors, enhancing their ability to kill tumor cells." (PMID 38734935, 2024). "TRPV1 channels regulate T-cell infiltration and migration in tumor tissues, thereby enhancing their ability to attack tumors." (PMID 38734935, 2024). "This decrease was associated with tumor size, metastases and poor prognosis, suggesting a tumor suppressant role of TRPV1." (PMID 39125864, 2024).
tumor (continued). "Noteworthy, intratumoral fibers present within the TME, with a significant share of TRPV1-expressing nerves, establish potential functional connectivity, leading to increased electrical activity in the tumor bed." (PMID 39906323, 2024). "NGF released by tumor cells can act on sensory nerves, especially on Transient Receptor Potential Vanilloid 1 (TRPV1)." (PMID 39723256, 2024). "In line with this concept, the downregulation of TRPV1 expression in mice promoted GC cell proliferation, invasion and dissemination, suggesting a tumor suppressant role of TRPV1." (PMID 39125864, 2024). "TRPV1 activation in macrophages promotes pro-inflammatory cytokine release, shaping the tumor immune environment and potentially sensitizing tumors to immune-mediated destruction." (PMID 39407657, 2024). "Here, the data suggest that tumor volume did influence behavior as at any given tumor volume the time to interact with the cookie is generally smaller in TRPV1-Cre::Floxed-DTA animals as compared to C57BL/6 animals." (PMID 39302290, 2024). "In recent years, researchers have delved deep into the role of TRPV1 in the context of tumorigenesis, particularly its involvement in tumor initiation, progression, and treatment modalities." (PMID 38567163, 2024). "In contrast, in vitro (over)expression of TRPV1 in mouse models of GC resulted in the inhibition of tumor proliferation, migration, tissue invasion and smaller tumor size." (PMID 39125864, 2024). "Several studies have indicated that tumor tissues from melanoma and ovarian cancer patients exhibit increased sensory innervation marked by TRPV1+ neurons when compared to healthy tissues." (PMID 38433844, 2024). "Adding to the confusion, the repeated activation of TRPV1-expressing sensory neurons was reported to promote tumor growth." (PMID 38339399, 2024). "In the case of mouse OS samples, seen as a similar osteoid mass, apparently the same level of expression was observed for both Trpa1 and Trpv1 in tumor cells." (PMID 38612571, 2024). "To date, most research into the effect of PSNs on the anti-tumor immune response has focused primarily on peptidergic nociceptors, specifically the Nav1.8+ TRPV1+ PSNs." (PMID 38433844, 2024). "It suggests that the TRPV1 blockade specifically suppresses the in vivo expression of stressful HSP70 at tumor site." (PMID 37120615, 2023). "The phenotypes of cisplatin-resistant tumor cells are dependent upon TRPV1, which is a direct transcriptional target of NANOG." (PMID 37165076, 2023). "Taken together, our findings indicate that the TRPV1 channel plays an important role in the secretory autophagy-dependent refractory phenotypes of NANOG+ tumor cells." (PMID 37165076, 2023). "For instance, TRPV1 is highly expressed in human colorectal cancer and related with tumor progression and inferior survival." (PMID 38129926, 2023). "The TUNEL staining was also utilized to assess the effect of TRPV1 blockade on the in vivo damages against the tumors from A549-WT and A549-TRPV1 KD tumor models upon thermotherapy." (PMID 37120615, 2023). "Firstly, immunofluorescence staining was applied to validate the TRPV1 expression in these malignant tumor cells using anti-TRPV1 primary antibody and Alexa Fluor 594 labeled secondary antibody." (PMID 37120615, 2023). "A uniform distribution at tumor stroma and intracellular space was observed for IS-Micelles, confirming deep and uniform penetration of TRPV1 antagonist and photothermal agent into tumor." (PMID 37120615, 2023). "Meanwhile, SB705498 (1.0 mg kg−1) was intratumorally injected at 30 min pre-irradiation for inducing TRPV1 blockade in A549-WT tumor models followed by tumor volumes monitoring during 30 days post-injection." (PMID 37120615, 2023). "Since both A549-WT and A549-TRPV1 KD cells had similar cellular uptakes of CuS-NCs, the knockdown of TRPV1 channel in tumor cells is reasonably involved in potentiating the hyperthermia-mediated thermo-cytotoxicity." (PMID 37120615, 2023).
tumor (continued). "The prognostic significance is based on the measurement of TRPV1 mRNA in tumor and control lung tissues, and is yet to be validated by immunostaining." (PMID 37240443, 2023). "Surprisingly, only TRPV1 was found to be sensitized to tumor-secreted factors in rat models of orofacial pain." (PMID 37111275, 2023). "We found that PTT evokes severe acute pain in mice, which correlates with increased tumor temperature and TRPV1 activation." (PMID 37153743, 2023). "For certain tumors, the TRPV1-mediated neuro-immune regulation of the tumor microenvironment enhances anti-tumoral immunity by inhibiting chronic inflammation." (PMID 37371563, 2023). "Taken together, we propose that NANOG+ tumor cells enriched by selective pressure imposed by cisplatin treatment preferentially expressed TRPV1 via transcriptional regulation." (PMID 37165076, 2023). "TRPV1 levels are significantly increased in T-cells isolated from B16F10 tumor-bearing mice.Possible role in anti-tumoral immune response and T-cell exhaustion requires further studies." (PMID 37371563, 2023). "In cancer therapy, TRPV1 hyperactivation promoted tumor initiation and progression and lead to alterations in tumor microenvironment during colorectal tumorigenesis." (PMID 36919561, 2023). "Beyond its physiological role in normal cells, the contribution of TRPV1 to tumor progression has also been widely investigated." (PMID 38129926, 2023). "In all these types of tumor cells, TRPV1 channels were mainly distributed in cell membrane as indicated by the obvious yellow fluorescence merged from the anti-TRPV1 antibody (red) and cell membrane probe (DiO, green)." (PMID 37120615, 2023). "From this perspective, it is possible that TRPV1 expression by other stemness factors also contribute to tumor progression and therapeutic resistance." (PMID 37165076, 2023). "There is, however, good evidence that TRPV1 is expressed in both sensory afferents and immune cells in the tumor microenvironment, as well as in the tumor cells themselves." (PMID 37240443, 2023). "Taken together, we propose that increased expression of HGF in SNs following TRPV1 activation plays a role as a paracrine coordinator of the crosstalk between SNs and BC in the acidic tumor microenvironment in bone." (PMID 37461623, 2023). "For instance, TRPV1 regulates cell proliferation in different tissues, including bone-derived tumor cells inducing cell proliferation in osteoblasts and cell apoptosis in osteoclasts lacking the TRPV1 and mineralization." (PMID 37507867, 2023). "As a result, TRPV1 blockade retrieves thermo-immunotherapy with tumor-eradicable and immune memory effects." (PMID 37120615, 2023). "Capsaicin activates DCs by binding to vanilloid receptor 1 or TRPV1 and affects cytokine secretion within the tumor environment, reducing immunosuppressive cells at the tumor site." (PMID 37705051, 2023). "When directly added to in vitro cultured mixed leucocytes, TRPV1 agonists differentially regulate cytokine secretion in tumor-bearing mice compared to controls." (PMID 37371563, 2023). "Tumor inoculation in the mouse femur led to a discernible increase in the ipsilateral TRPV1 expression within the DRGs." (PMID 37664239, 2023). "Previous studies reported that VEGF signaling increases the expression of TRPA1 as well as TRPV1 channels in afferent terminals innervating tumor cells." (PMID 35077502, 2022). "In present of DDP, the tumor weight and growth of TRPV1 overexpression group were significant increased compared with the empty vector group, which indicated that TRPV1 overexpression induced DDP resistance in vivo." (PMID 35402237, 2022). "Over the last two decades, TRPV1 has been shown to play multiple roles in tumorigenesis and tumor development." (PMID 35402237, 2022). "Firstly, we analyzed the levels of TRPV1 mRNA expression using the online RNA‐Seq datasets of multiple tumor types." (PMID 35620019, 2022).